JAG1 (jagged canonical Notch ligand 1)
Diseases named in the same sentence as JAG1 in open-access papers (continued):
Sharing a sentence is not in itself a finding about the gene and the disease.
esophageal squamous cell carcinoma (2 papers, 2023 to 2024). Esophageal squamous cell carcinoma (ESCC) is a type of esophageal carcinoma (EC) that can affect any part of the esophagus, but is usually located in the upper or middle third. "Importantly, expression levels of JAG1/2 are lower in the early stages of human esophageal squamous cell carcinoma (ESCC) carcinogenesis." (PMID 38750026, 2024).
Failure to thrive (2 papers, 2021 to 2024). Failure to thrive (FTT) refers to a child whose physical growth is substantially below the norm. "Given the uncertainty surrounding how JAG1 affects CH development, it might be beneficial to include routine thyroid function assessments for ALGS patients, particularly those experiencing failure to thrive." (PMID 38245625, 2024).
gallbladder cancer (2 papers, 2017 to 2023). "It is also likely that Kras- mediated Notch deregulation promotes tumor development in a subset of gallbladder cancer patients, and targeting Notch2/3 and Jag1 could be a therapeutic approach for these patients." (PMID 29142904, 2017).
giant cell arteritis (2 papers, 2020 to 2021). "By analyzing gene expression in tissue from arteries of patients with giant cell arteritis and healthy individuals, Wey and colleagues found abundant expression of JAG1 and NOTCH1 in vasculitic arteries." (PMID 33912195, 2021).
glaucoma (2 papers, 2011 to 2025). Increased pressure in the eyeball due to obstruction of the outflow of aqueous humor. "This case addresses an important gap in the literature by highlighting the potential role of JAG1 mutations in anterior segment dysgenesis and their implications in glaucoma development." (PMID 41293383, 2025). "Given JAG1's role in Notch signaling and mesodermal development of anterior segment structures, this variant could plausibly contribute to mesodermal dysgenesis and to glaucoma." (PMID 41293383, 2025). "Thus, understanding the developmental pathway of these ocular structures provides insight into how JAG1 mutations may predispose ALGS patients to glaucoma." (PMID 41293383, 2025).
hepatopathies (2 papers, 2021 to 2026). "We tested this approach on 9 patients with pediatric hepatopathies with phenotypes ranging from the full clinical ALGS spectrum to isolated neonatal cholestasis and atypical ALGS abnormalities who carried 5 JAG1 and 3 NOTCH2 missense variants of interest." (PMID 41998240, 2026).
hypothyroidism (2 papers, 2020). Abnormally low levels of thyroid hormone. "Similarly, the association between variants in PTPN11 and hypothyroidism as well as the association between JAG1 and birth weight were reported." (PMID 33226994, 2020).
ischemia (2 papers, 2012 to 2020). A hypoperfusion of the BLOOD through an organ or tissue caused by a PATHOLOGIC CONSTRICTION or obstruction of its BLOOD VESSELS, or an absence of BLOOD CIRCULATION. "Focal ischemia has been shown to downregulate the expression of miR-124 in neural progenitor cells residing in the subventricular zone; miR-124 transfection reduces the ischemia-induced proliferation via suppression of Jagged-1 (JAG1) membrane protein involved in modulating Notch signaling pathway." (PMID 32937836, 2020). "EA pretreatment significantly enhanced Notch1, Notch4 and Jag1 gene transcriptions in the striatum, except Notch1 intracellular domain level, which could be increased evidently by ischemia." (PMID 22989188, 2012).
kidney failure (2 papers, 2018 to 2022). An acute or chronic condition that is characterized by the inability of the kidneys to adequately filter the blood. "Our studies can provide the foundation for the development of novel molecular therapeutics for kidney failure and advance our understanding of the renal effect of JAG1 antagonism-based therapies." (PMID 30226866, 2018).
Lewis Lung Carcinoma (2 papers, 2015 to 2017). "JAG1 overexpression in Lewis lung carcinoma cells accelerated tumor growth in vivo, but this effect was prevented in Lgals3−/− mice." (PMID 28533486, 2017). "Lewis lung carcinoma cells (LLC) were transduced with an empty vector retrovirus (LLC-EV), JAG1-encoded retrovirus (LLC-JAG1) or DLL4-encoded retrovirus (LLC-DLL4) and implanted subcutaneously into C57black/6 Lgals3+/+ or Lgals3−/− mice." (PMID 28533486, 2017).
liver inflammation (2 papers, 2020 to 2022). "Similarly, JAG1-MSC treatment further decreased inflammatory mediators, whereas Notch2 silence abolished the beneficial effect of JAG1-MSCs on APAP-induced liver inflammation." (PMID 35842731, 2022). "Our results highlight the importance of JAG1-mediated myeloid Notch1/HSF1/Snail signaling as a key regulator of NLRP3 activation and cell apoptosis during IR stress-mediated liver inflammation." (PMID 31673056, 2020).
lymph node metastasis (2 papers, 2022 to 2025). "High JAG1 expression was significantly linked to advanced lymph node metastasis, distant metastasis, and the TNM stage." (PMID 36539520, 2022). "The results confirmed that JAG1 was significantly associated with lymph node metastasis (χ2 = 15.034, P < 0.001), distant metastasis (χ2 = 11.148, P = 0.001), and the TNM stage (χ2 = 12.215, P = 0.002)." (PMID 36539520, 2022). "Correlation analysis confirmed that high JAG1 expression was significantly correlated to advanced lymph node metastasis, distant metastasis, and the TNM stage." (PMID 36539520, 2022).
nasopharyngeal carcinoma (2 papers, 2016 to 2018). A carcinoma arising from the nasopharyngeal epithelium. "MiR-26b is prominently down-regulated in DDP-resistant nasopharyngeal carcinoma cells and induces cisplatin resistance by repressing Jagged 1(JAG1)." (PMID 29642855, 2018).
Nephropathy (2 papers, 2018 to 2020). A nonspecific term referring to disease or damage of the kidneys. "Transcript analysis of mouse kidney disease models, including folic-acid (FA)–induced nephropathy, unilateral ureteral obstruction (UUO), or apolipoprotein L1 (APOL1)-associated kidney disease, indicated that Jag1 and Notch2 levels were higher in all analyzed kidney fibrosis models." (PMID 30226866, 2018).
oral cancer (2 papers, 2022 to 2023). "In oral cancer, PTTG3P acts as a ceRNA for JAG1 by sponging miR-142-5p, leading to increased JAG1 translation and enhanced cancer cell proliferation." (PMID 37627052, 2023).
pancreatic adenocarcinoma (2 papers, 2011 to 2021). "Interestingly, analysis in TCGA pancreatic adenocarcinoma data set found a positive correlation between JAG1 and SOX9 expressions, and high SOX9 mRNA level is associated with poor overall survival, whereas low SOX9 expression is associated with significantly longer survival." (PMID 33268505, 2021).
periodontitis (2 papers, 2022 to 2024). An acute or chronic inflammatory process that affects the tissues that surround and support the teeth. "Therefore, we propose that targeting the JAG1-Notch pathway could not only reduce the local inflammation associated with periodontitis but also have a positive clinical impact on systemic diseases such as metabolic syndrome." (PMID 39769019, 2024). "While our study reveals the potential role of JAG1 in periodontitis and provides initial validation through a mouse model, we acknowledge several limitations in our current research." (PMID 39769019, 2024). "Validation through animal experiments revealed that JAG1 inhibition reduces inflammation in epithelial cells, mitigating periodontitis." (PMID 39769019, 2024). "To validate the role of the JAG1–NOTCH2 axis in periodontitis, we employed a ligature-induced periodontitis mouse model and administered localized siRNA to suppress JAG1 expression." (PMID 39769019, 2024). "We discovered a regulatory mechanism involving the JAG1–Notch signaling axis between basal epithelial cells and M1-type macrophages, which plays a critical role in the progression of periodontitis." (PMID 39769019, 2024). "Spatial transcriptomics further confirmed that JAG1 expression in basal epithelial cells was markedly increased in the context of periodontitis, with concurrent upregulation of NOTCH2 in macrophages." (PMID 39769019, 2024). "Interestingly, both species exhibited JAG1–NOTCH2 ligand–receptor interactions, highlighting a common mechanism for epithelial cell–M1 macrophage communication during periodontitis." (PMID 39769019, 2024).
plasma cell leukemia (2 papers, 2016 to 2023). An aggressive plasma cell neoplasm characterized by the presence of neoplastic plasma cells in the peripheral blood. "However, a previous gene expression profiling study conducted on a proprietary dataset of 129 MM cases indicated that JAG1 was overexpressed in MM compared to normal controls, with the highest expression levels observed in primary plasma cell leukemia." (PMID 37834003, 2023).
preeclampsia (2 papers, 2015 to 2021). Preeclampsia is a hypertensive disorder of pregnancy that is characterized by new-onset hypertension with proteinuria presenting after 20 weeks of gestation, and depending on mild or severe forms may initially present with severe headache, visual disturbances, and hyperreflexia. "While it is not certain whether the birth weight associated SNP near JAG1 acts primarily via fetal or maternal mechanisms, a reduced expression of JAG1 in placentas from pregnancies complicated with preeclampsia has been observed." (PMID 33682876, 2021).
prostate adenocarcinoma (2 papers, 2015 to 2022). "For this end, we crossed the endothelial Jag1 mutants to a mouse model of prostate adenocarcinoma (TRAMP), which spontaneously develop prostatic lesions from 8 weeks of age." (PMID 26213336, 2015).
retinoblastoma (2 papers, 2016 to 2019). A malignant tumor that originates in the nuclear layer of the retina. "Since we observed that Jag2 mRNA and protein levels were more elevated than Jag1 in both retinoblastoma lines, and also upregulated compared to normal adult retina, we decided to also genetically inhibit Notch signaling by downregulating expression of this Notch ligand." (PMID 27661116, 2016). "A series of canonical pathways, including those involved in Rb (Retinoblastoma)/E2F cell cycle (Rb, E2f2, E2f3, E2f5, Cdk6, DHFR), Notch (Dll1, Notch 2, Jag1), Wnt (Wnt, Axin2, Wisp2/Ccn5) and NF-κB (Ikbip) were found to participate in this network." (PMID 30742662, 2019).
Sepsis (2 papers, 2015 to 2022). Sepsis is defined as life-threatening organ dysfunction caused by a dysregulated host response to infection. "Further, the aortic mRNA expressions of both Jag1 and Dll4 ligands were also significantly (p < 0.05) down-regulated in sepsis." (PMID 35190630, 2022).
thyroid (2 papers, 2024). "Regarding JAG1, variations in this gene have been related to the pathogenesis of various thyroid disorders, including CH." (PMID 38790508, 2024). "Generally, various genetic and molecular studies addressed the issue of congenital hypothyroidism (for example, anomalies of TSHR, SLC26A7, JAG1, DUOX2, and FOXE1 gene) linking the thyroid dyshormonogenesis to thyroid dysgenesis." (PMID 38791947, 2024).
thyroid dysgenesis (2 papers, 2021 to 2025). "Among the eight patients with thyroid dysgenesis, seven carried a single JAG1 variant, suggesting that JAG1 variants primarily cause thyroid dysgenesis through a monogenic model." (PMID 41303336, 2025). "Moreover, among 100 unrelated patients with CH, they reported two heterozygous JAG1 variants in four patients (three with thyroid dysgenesis)." (PMID 41303336, 2025). "Therefore, current data support the role of JAG1 mutations in the pathogenesis of thyroid dysgenesis, justifying the examination of these mutations in molecular studies." (PMID 41303336, 2025).
abortion (1 paper, 2023). the ending of pregnancy by removing a fetus or embryo before it can survive outside the uterus. "qPCR was performed in placentas and the results showed decreased Jag1, Notch3 and Hes1 mRNA levels in LPS‐induced abortion mouse model compared with the control (n = 3/group)." (PMID 37272232, 2023). "In addition, GDF15 could serve as a pro‐invasive factor in human extravillous trophoblasts and upregulate JAG1/NOTCH3/HES1 pathway activity as well as rescue the embryo absorption phenotype observed in the LPS‐induced abortion mouse model." (PMID 37272232, 2023).
acute coronary syndrome (1 paper, 2022). Signs and symptoms related to acute ischemia of the myocardium secondary to coronary artery disease. "A recent study revealed that upregulation of miR-335-5p could reduce atherosclerotic vulnerable plaque formation in acute coronary syndrome by targeting Jagged1 (JAG1) through regulating Notch signaling." (PMID 35235755, 2022).
aneurysm (1 paper, 2022). Bulging or ballooning in an area of an artery secondary to arterial wall weakening. "Our observations shed more light on the pathomechanisms behind aneurysm formation in JAG1 variant harboring individuals and underline the importance of cardiovascular imaging in the clinical follow‐up of such individuals." (PMID 35819173, 2022).
Anxiety (1 paper, 2017). Intense feelings of nervousness, tension, or panic often arise in response to interpersonal stresses. "We previously reported anxiety-related differential methylation of JAG1 and JAG2 in the central nucleus of the amygdala of young monkeys;26 here we find anxiety-related differential methylation of JAG2 in humans." (PMID 29225348, 2017).
carcinoma in situ (1 paper, 2024). "More than half of the Jag1/2 KO mice developed carcinoma in situ or invasive SCC, whereas the majority of the WT or the p63CreERT2/+ mice only displayed epithelial hyperplasia or dysplasia." (PMID 38750026, 2024).
Cerebellar hypoplasia (1 paper, 2022). Cerebellar hypoplasia is a descriptive term implying a cerebellum with a reduced volume, but a normal shape and is stable over time. "Interestingly, supplementation of ex vivo cerebellar slices from preterm pigs with recombinant Jag1 protein rescued GCP proliferation, further supporting the role of Jag1 as an essential mediator of the preterm cerebellar hypoplasia phenotype." (PMID 36523506, 2022).
chordoma (1 paper, 2013). Chordomas are rare malignant tumors arising from embryonic remnants of the notochord in axial skeleton. "Six genes (NOTCH2, NCOR2, CREBBP, JAG1, KAT2A and NCSTN) related to the Notch signaling pathway were upregulated in chordoma tissues." (PMID 23826111, 2013).
chronic myelomonocytic leukemia (1 paper, 2019). A myelodysplastic/myeloproliferative neoplasm which is characterized by persistent monocytosis, absence of a Philadelphia chromosome and BCR/ABL fusion gene, fewer than 20 percent blasts in the bone marrow and blood, myelodysplasia, and absence of PDGFRA or PDGFRB rearrangement. "Similarly, conditional loss of nuclear factor kappa B (NFkB) inhibitor in stromal cells causes upregulation of JaG1/Notch signaling in HSPCs, resulting in a disorder similar to chronic myelomonocytic leukemia (CMML)." (PMID 31861268, 2019).
colorectal adenoma (1 paper, 2020). An adenoma that arises from the colon or rectum. "We investigated mRNA expression of four Notch receptors (Notch1–4), five ligands (Jag1, Jag2, Dll1, Dll3, and Dll4), and four target genes (Hes1, Hes5, Hey1, and Hey2) using highly specific TaqMan gene expression assays in colorectal adenomas and cancers." (PMID 32211044, 2020).
cryptorchidism (1 paper, 2025). The failure of one or both testes of a male fetus to descend from the abdomen into the scrotum during the late part of pregnancy. "Hypospadias and cryptorchidism are common findings in patients affected by NOTCH2 variants, compared to those with JAG1 variants." (PMID 40806755, 2025).
cystic neoplasm (1 paper, 2021). A benign or malignant neoplasm that contains a single or multiple cystic spaces. "Thus, deletion of Jag1 was associated with significantly increased incidence of cystic neoplasms and decreased incidence of PDAC (χ2 test, P < 0.0001), suggesting a switch from ductal adenocarcinoma to cystic neoplasms." (PMID 33268505, 2021). "This study revealed a Jag1-controlled phenotypic switch between PDAC and largely benign cystic neoplasms, which appeared to be associated with differential expression of Lkb1 and Sox9 in pancreatic ductal cells." (PMID 33268505, 2021). "Thus, Jag1 expression was lost in cystic neoplasms but retained in the invasive carcinoma in KJC mice." (PMID 33268505, 2021). "With the same Sox9-CreER, concurrent Lkb1 deletion and Kras activation in the ductal epithelium resulted in IPMN in adult mice, whereas deletion of Jag1 combined with KrasG12D expression in the ductal epithelium failed to induce cystic neoplasm." (PMID 33268505, 2021). "In this study, deletion of Jag1 in conjunction with oncogenic KrasG12D expression in the mouse pancreas induced rapid development of acinar-to-ductal metaplasia and early stage pancreatic intraepithelial neoplasm; however, culminating in cystic neoplasms rather than ductal adenocarcinoma." (PMID 33268505, 2021).
Depression (1 paper, 2025). "Depression-associated pairs spanned Notch (JAG1-NOTCH2, DLL1-NOTCH3, DLL4-NOTCH3), ephrin (EFNA5-EPHA5, EFNA5-EPHA7, EFNA5-EPHA4), and extracellular matrix pathways (SLIT1-ROBO1, NTN1-DCC)." (PMID 40964296, 2025).
ductal carcinoma in situ (1 paper, 2012). "Overexpression of NOTCH receptors has been implicated in ductal carcinoma in situ (DCIS) and invasive breast cancer, and high levels of the NOTCH ligand JAG1 appear to predict a poor overall survival." (PMID 22992387, 2012).
dystocia (1 paper, 2022). Slow or difficult obstetric labor or childbirth. "We injected pregnant dams at E10.5 with 1 mg of tamoxifen and concomitant 0.25 mg of progesterone to minimize the incidence of dystocia, and a Jag1 deletion efficiency of 68% ± 14% was achieved in aortic SMCs of newborn pups." (PMID 34990407, 2022).
epithelial dysplasia (1 paper, 2024). "Histological analysis showed elevated squamous epithelial barrier damage, severe epithelial dysplasia, and inflammatory cell accumulation in the Jag1/2 KO forestomach." (PMID 38750026, 2024). "Moreover, Jag1/2 KO mutants also exhibited more severe epithelial dysplasia in the esophagus and tongue." (PMID 38750026, 2024). "Our results showed that the absence of Jag1/2 significantly exacerbated squamous epithelial injury in the forestomach, resulting in more severe inflammation and epithelial dysplasia." (PMID 38750026, 2024).
Familial exudative vitreoretinopathy (1 paper, 2023). Familial exudative vitreoretinopathy (FEVR) is a rare hereditary vitreoretinal disorder characterized by abnormal or incomplete vascularization of the peripheral retina leading to variable clinical manifestations ranging from no effects to minor anomalies, or even retinal detachment with blindness. "Mutations in JAG1 have been associated with familial exudative vitreoretinopathy (FEVR) and is characterized by incomplete vascularization of the peripheral retina." (PMID 36830640, 2023).
focal segmental glomerulosclerosis (1 paper, 2018). A renal disorder characterized by sclerotic lesions in the glomeruli. "Conversely, the de-repression of Jag1, which encodes jagged 1, facilitated podocyte dedifferentiation, increasing the susceptibility to focal segmental glomerulosclerosis (FSGS)." (PMID 30459215, 2018).
gallbladder tumor (1 paper, 2017). "We also determined the effect of Jag1 deletion on Kras-induced gallbladder tumor development." (PMID 29142904, 2017).
HCMV infection (1 paper, 2017). "Human NPCs are fully permissive for HCMV replication, and our previous work has demonstrated that HCMV infection dysregulates NICD1 and Jag1 in NPCs, which are two essential components upstream of Hes1 in the Notch signaling pathway." (PMID 28750047, 2017).
Heterotaxy (1 paper, 2021). An abnormality in which the internal thoraco-abdominal organs demonstrate abnormal arrangement across the left-right axis of the body. "In this study, we delineated the low levels of JAG1, which is a Notch ligand, in the patent DA with heterotaxy syndrome." (PMID 33923468, 2021).